EGFR (epidermal growth factor receptor)
Diseases named in the same sentence as EGFR in open-access papers (continued):
Sharing a sentence is not in itself a finding about the gene and the disease.
breast carcinoma (continued). "In recent years, a study confirmed that YTHDF3 promotes breast cancer metastasis by promoting the translation of ST6GALNAC5, GJA1 and EGFR." (PMID 35197112, 2022). "For example, Liang and coworkers used a combination of gefitinib, an EGFR inhibitor, and GD3S knockdown by shRNA to treat mice infected with breast cancer cells, and observed a suppression of tumor growth." (PMID 35267607, 2022). "Among these compounds, compound 25 has a promising potency for VEGFR2 and EGFR (IC50 = 19.8 nM and 11.4 nM, respectively), and stronger antitumor effects on human breast cancer cell lines MCF-7 compared with that of molecule 1 and EGFR inhibitor erlotinib." (PMID 35799213, 2022). "Pyrotinib is an emerging irreversible EGFR/HER2 dual TKI and has been approved in HER2‐positive breast cancer in China." (PMID 36254250, 2022). "ERBB2 is HER2, a member of the epidermal growth factor receptor (EGFR) family which is often overexpressed in breast cancer and an effective drug target in treating HER2-positive breast cancer." (PMID 35681777, 2022). "As an additional control, we targeted HER2 signaling using the dual EGFR/HER2 tyrosine kinase inhibitor lapatinib and assessed SorLA levels in the lapatinib‐sensitive HER2+ BT‐474 and SK‐BR‐3 breast cancer cells." (PMID 34564954, 2022). "EGFR is known to be the key promoter of multiple cancers (e.g. NSCLC, breast cancer), and FOSL1 has been confirmed to be indirectly targeted by circCRIM1." (PMID 35484574, 2022). "Another study combined EGFR‐CAR NK‐92 cells with oncolytic herpes simplex virus (oHSV) increased cytolytic effect and IFN‐γ production when co‐cultured with breast cancer cell lines MDA‐MB‐231, MDA‐MB‐468, and MCF‐7 in vitro compared to monotherapies." (PMID 35762299, 2022). "Probably the best-known anti-cancer mAb is trastuzumab (Herceptin) which is used against breast cancer positive for HER2, a member of the epidermal growth factor receptor (EGFR) family." (PMID 35681682, 2022). "TAM exerts its function as a GPR30 agonist that activates the epidermal growth factor receptor (EGFR) intracellular signaling, MAPK and PI3K/AKT signaling pathways, leading to TAM resistance in breast cancer." (PMID 35330066, 2022). "Overexpression of EGFR was reported in breast cancer including TNBC (triple-negative breast cancer) and other types of breast cancer." (PMID 36412852, 2022). "In HER2-amplified breast cancer, increased level of HER ligands due to treatment with trastuzumab led to an increase in active EGFR/HER3 dimers to promote resistance." (PMID 35565268, 2022). "In early-stage breast cancer, DDX5 expression along with overexpression of EGFR and Ki67, a nuclear marker for cell proliferation, positively correlates with a poor prognosis and invasiveness of tumors, a high risk of recurrence and worse survival in patients." (PMID 35954483, 2022). "It has confirmed that EGFR phosphorylation was regulated by ITGB4 in gastric cancer, breast cancer and liver cancer." (PMID 34975337, 2022). "For example, EGFR and HER2 co-express in human bladder cancer and colorectal cancer cell lines and SKBR3 human breast cancer cells." (PMID 35612280, 2022). "Together, these drugs targeting multiple receptors, such as HER2, EGFR and HER4, were studied in the early and advanced stages of breast cancer and revealed some promising outcomes." (PMID 36187116, 2022). "Suppressed VCAN expression blocks breast cancer cell self-renewal, while overexpression of the G3-domain of VCAN promotes cancer cell self-renewal via the EGFR/AKT/GSK3β pathway." (PMID 36358747, 2022). "EGFR content was highest in human epidermoid cell carcinomas (A431) compared to human cervical cancers (HeLa) or human breast cancers (MCF-7), as quantified by the ratio of EGFR-band vs actin-band intensities (%)." (PMID 36499115, 2022). "Using the breast cancer cell lines MCF-7 and MDA-MB-231, we observed that masitinib inhibits the activity of mTOR, a downstream effector of EGFR." (PMID 36204232, 2022).
breast carcinoma (continued). "In the breast cancer cell lines IJG-1731, BT20, and MDA-MB-468, EGFR phosphorylation is stimulated by epidermal growth factor and IL-17E." (PMID 35954312, 2022). "Research shows that syringin can exert anti-breast cancer effects through PI3K-AKT and EGFR-RAS-RAF pathways, and their study revealed that Acanthopanax senticosus polysaccharide (ASPS) plays a major role in regulating immune damage caused by radiation." (PMID 36110515, 2022). "One study reported that ROS levels in BRCA1 and basal-like breast cancer correlated with AhR expression and this increased expression of amphiregulin (AREG), a ligand for the epidermal growth factor receptor (EGFR)." (PMID 36428667, 2022). "In breast cancer, GABRP was found to control the stemness of triple-negative breast cancer cells through epidermal growth factor receptor signaling." (PMID 35967794, 2022). "In this study, m708.5 exhibited very strong synergy with the epidermal growth factor receptor (EGFR) inhibitor gefitinib, and synergy with chemotherapeutic agents in vitro against either neuroblastoma or breast cancer cells." (PMID 35399718, 2022). "Three other breast cancer cell lines, namely MDA-MB-231, MDA-MB-157 and T47D, underwent aerotaxis independently of EGF and EGFR." (PMID 36380366, 2022). "Previous studies have shown overexpression of mesenchymal markers EGFR, CSV and SNAI1 after treatment with nab-paclitaxel in breast cancer cell lines." (PMID 35719960, 2022). "Pyrotinib is a potent epidermal growth factor receptor/human epidermal growth factor receptor 2 (EGFR/HER2) inhibitor and can be used to treat HER2-positive breast cancer." (PMID 36160438, 2022). "Furthermore, EGFR may play an important role in primary lung adenocarcinomas and breast cancer." (PMID 36313724, 2022). "In breast cancer cells, Ras expression was reflected in high mitogen-activated protein kinase (MAP kinase) activity as well as EGFR (Epidermal Growth Factor Receptor) and erbB-2 overexpression." (PMID 35453754, 2022). "Jab1/CSN5 is also a target of EGFR signaling, and activation of EGFR promotes the translocation of Jab1/CSN5 from the cytoplasm to the nucleus in breast cancer cells." (PMID 35315259, 2022). "AREG (amphiregulin), a member of the EGF family and a ligand for EGFR or TNF-alpha receptor, is involved in the initiation and progression of breast cancer." (PMID 35681777, 2022). "Amplification of some oncogenes in breast cancer, especially in the TNBC type, is very common, such as EGFR, E2F, CCND1, Myc, Ras and Notch." (PMID 35892755, 2022). "The potential crosstalk of EGFR and NK1R has been described in breast cancer and glioblastoma, showing that NK1R activation affected EGFR phosphorylation and downstream signaling pathways, thus regulating cancer cell proliferation and drug sensitivity." (PMID 35013118, 2022). "For the two patients who had targeted therapy (case 1 and 2), both of them received inhibitors of the EGFR/HER2 pathway during their course of lung and breast cancer therapy, respectively." (PMID 35572995, 2022). "We also found EGFR, MYCN, and MYC in brain cancers;39,40BCL2, MYC, and the loci of IGH translocations in lymph-nodes cancer;41–43CDK12 in breast cancer; CCND1 in liver cancer; and RUNX1, GATA6, and PDE4D in esophageal cancer." (PMID 36163358, 2022). "By stably overexpressing one of the four genes EGFR, HER2, RAF, or MEK in the estrogen receptor (ER)-positive MCF7 breast cancer cell line, Creighton and colleagues established cell lines with hyperactivation of the MAPK pathway." (PMID 36358725, 2022). "Here we report a case of robust glycemia and HbA1c normalization in a patient with breast cancer-T2D comorbidity under neratinib, a potent triple kinase inhibitor of HER2/EGFR and MST1." (PMID 35370966, 2022). "It explicitly inhibits EGFR and ERBB2 tyrosine kinase receptors in tumor cells, showing better therapeutic efficacy and limited toxicity in gallbladder and breast cancers than GW-572016." (PMID 36476719, 2022).
breast carcinoma (continued). "For example lapatinib (dual anti-EGFR and HER2 inhibitor), used for the treatment of breast cancer 28, appears frequently in PaSSS analysis as a suggested drug in mono- or combined treatments for HNSCC." (PMID 35154483, 2022). "For instance, ECM1 activated the epidermal growth factor receptor (EGFR) signaling pathway and facilitated the progression of breast cancer cells and their resistance to trastuzumab treatment." (PMID 36408224, 2022). "OGN can reverse EMT through the PI3K/Akt/mTOR pathway in breast cancer, and reduce the expression of ZEB-1 through the EGFR/Akt signaling pathway in colon cancer to inhibit EMT." (PMID 35513835, 2022). "Approximately 15–20% of breast cancers overexpress HER2, a tyrosine kinase receptor that is a member of the epidermal growth factor receptor (EGFR) family." (PMID 35142964, 2022). "When it comes to breast cancer, TNBC has a higher rate of EGFR overexpression than other subcategories." (PMID 36188649, 2022). "Moreover, previous studies have shown that regulation of protein localization changes is associated with EGFR/ERK and EGFR/AKT signaling activation in tamoxifen-resistant breast cancer cells, indicating that this may be a potential target for enhancing chemosensitivity of breast cancer patients." (PMID 35335125, 2022). "In breast cancers, GEF100, another GEF protein of ARF6, has been shown to bind Tyr1068/1086-phosphorylated EGFR to activate Arf6 to induce TNBC invasion and metastasis." (PMID 36224181, 2022). "We have investigated in cell models representative of the major subtypes of breast cancer (BC) the interplay between the chemokine CXCL12/CXCR4/ACKR3 and EGF receptor (EGFR) family signaling cascades." (PMID 36233192, 2022). "They found that YTHDF3 promoted the binding between eukaryotic initiation factor 3 and angiogenic transcripts, such as VEGFA and epidermal growth factor receptor (EGFR), indicating its potential role as a therapeutic target in breast cancer." (PMID 36291060, 2022). "Previous studies have also reported that Se/FO supplements target EGFR/TβR/AXL/PI3K/Akt/mTOR signaling and therefore increase the apoptotic efficacy of anti-cancer agents in breast-cancer-bearing mice and NSCLC cells." (PMID 36547898, 2022). "Already approved HER kinase inhibitors are mainly for EGFR‐mutant NSCLC and HER2‐positive breast cancer." (PMID 36254250, 2022). "The IC50 afatinib values for the whole primary NSCLC cell line panel of 4.81 ± 2.05 μM is a typical result for cell lines not dependent on mutated EGFR, such as breast cancer cell lines T47D and BT20, whereas IC50 values for afatinib and cell lines addicted to mutated EGFR may be as low as 6–10 nM." (PMID 34596822, 2022). "Dimerization of EGFR and HER2 receptors mediates ACTA2 overexpression through the JAK2/STAT1-dependent signaling pathway to trigger motility of breast cancer cells." (PMID 35954483, 2022). "PTPN9 suppresses the growth and invasion of breast cancer cells by negatively regulating HER2 and epidermal growth factor receptor (EGFR) and suppressing STAT3 activation." (PMID 35957898, 2022). "The combination of INCB3619, a potent inhibitor of ADAM10 and ADAM17, with GW-2974, a dual inhibitor of EGFR and HER-2/neu kinases, resulted in a synergistic growth inhibitory effect on MCF-7 and HER-2/neu-transfected MCF-7 human breast cancer cells." (PMID 36476719, 2022). "Varlitinib, an EGFR/HER2 inhibitor and anti-breast cancer drug, is FDA approved for the treatment of breast cancer and is known to cross the blood–brain barrier." (PMID 36341365, 2022). "The type I (EGFR-related) involved in the biological behavior of breast cancer cells is HER2 growth factor receptor, which gene is overexpressed in about 15–20% of breast cancers and represents a worse prognosis." (PMID 35874525, 2022).
breast carcinoma (continued). "Therapeutic decisions in breast cancer (BC) are, among other factors, based on the expression of the predictive markers on the primary tumor (PT): the estrogen-(ER) and progesterone receptor (PR) as well as the epidermal growth factor receptor HER2." (PMID 35025065, 2022). "Neratinib is a more potent inhibitor than the dual EGFR/HER2 tyrosine kinase inhibitor (TKI) Lapatinib, potentiating the cytotoxic effect of trastuzumab in HER2+ breast cancer cell lines." (PMID 34556812, 2021). "Cytotoxic effect was related to the suppression of activation of EGFR and HER2 by interfering with the phosphorylation of these receptors in the plasma membrane of breast carcinoma cells." (PMID 34874400, 2021). "In breast cancer, HOXB5 enhanced cell growth and invasion partly through RET, ERBB2, EGFR, and ESR1." (PMID 34440097, 2021). "In this study, we found that the EGFR and Src-mediated STAT3 signalling pathway was significantly activated in breast cancer cells with acquired resistance to tamoxifen through gene set analysis and protein expression screening." (PMID 34407787, 2021). "Utilizing a phosphoprotein array comprising of 46 specific Ser/Thr/Tyr phosphorylation sites of 38 selected proteins, we found elevated levels of phosphorylated ERK, EGFR and MSK in tamoxifen resistant breast cancer cells." (PMID 34389732, 2021). "These cell lines represent the patient-derived TNBC subset from the TCGA dataset: the PaSSS of MDA-MB-468 included EGFR and estrogen receptor, ER, as central targets, thereby corresponding to ~31% TNBC tissues in the TCGA breast cancer subset." (PMID 34638492, 2021). "On 13 March 2007, the FDA approved the third EGFR-TKI, lapatinib, in combination with capecitabine for the treatment of breast cancer." (PMID 34771085, 2021). "We next examined the functional correlation between EGFR activation and the sensitivity to T-DM1 in a different breast cancer cell line, SKBR-3, a HER2-positive breast cancer cell line that is very sensitive to T-DM1." (PMID 34066157, 2021). "In this study, we investigated the roles of the EGFR and Src-mediated STAT3 signalling pathway in tamoxifen-resistant breast cancer (TamR) cells." (PMID 34407787, 2021). "For ErbB signaling, Ohno etal. demonstrated in 2013 that engineered, systemically injected Exos were able to target specifically EGFR‐expressing breast cancer cells thereby effectively delivering microRNAs." (PMID 33207034, 2021). "In luminal B breast cancer, membrane receptors such as HER2, HER3, and EGFR (HER1) can reside and interact within cholesterol enriched domains, thus creating activated receptor platforms that support rapid signaling." (PMID 33001587, 2021). "Pyrotinib, another emerging irreversible epidermal growth factor receptor (EGFR)/HER2 dual TKI, has been approved in HER2-positive breast cancer in 2018 in China." (PMID 34530760, 2021). "At the molecular level, HER2 overexpression in ER+ breast cancer cells suffices to drive tamoxifen resistance, and elevated levels of EGFR and HER2 are detected in tamoxifen-resistant clones following long-term exposure of ER+ breast cancer cells to tamoxifen." (PMID 33800852, 2021). "Here, we report that degradation of an endosomal small GTPase, RhoB, by the ubiquitin ligase complex cullin-3 (CUL3)/KCTD10 is essential for both EGFR and HER2 phosphorylation in HER2-positive breast cancer cells." (PMID 34187934, 2021). "In HER-positive breast cancer, the secretion of FGF5 by CAFs leads to FGFR2 activation in cancer cells and acquisition of resistance to trastuzumab and lapatinib (EGFR/HER2 inhibitors) through FGFR2/c-Src-mediated HER2 transactivation." (PMID 34830951, 2021).
breast carcinoma (continued). "Next to breast cancer models, mice bearing human glioblastoma U87MG (EGFR/CD105+/+) tumors were used to examine the potential of endoglin-based imaging." (PMID 33946583, 2021). "One important reason for different patterns of breast cancer incidence was genes, and it was confirmed that BRCA1/2, HER2, Epidermal Growth Factor Receptor (EGFR), and c-Myc have played key roles in the processes of breast cancer." (PMID 34744569, 2021). "Further exploration of the direct involvement of Her2 and EGFR in leptin-mediated Med1 phosphorylation showed increased activation of EGFR, ERK, and Her2 in leptin treated breast cancer cells." (PMID 34389732, 2021). "Although it has been recently reported that TMEM16A activated EGFR signaling pathway in HNSCC, breast cancer and pancreatic cancer." (PMID 33816307, 2021). "A previous study suggested that both EGFR and AKT are upstream signaling activators of YB-1 and are essential for controlling YB-1 activation in breast cancer." (PMID 34696665, 2021). "HER2 belongs to the human epidermal growth factor receptor (EGFR) family and is an oncogenic driver to be well used as the marker of prognosis and therapeutic target in ovarian and breast cancers; it also plays a key factor in CRC." (PMID 33564344, 2021). "A well-known cancer-related report showed the successful generation of breast cancer-targeting EVs using the GE11 peptide, which binds to epidermal growth factor receptor (EGFR) but is less mitogenic than EGF, targeting EGFR." (PMID 34885247, 2021). "For example, G-1 stimulates proliferation in primary breast cancer tissue and the GPER antagonist G-36 completely inhibits G-1-mediated proliferation; G-1 enhances ovarian cancer cell proliferation via EGFR and Akt signaling pathways." (PMID 34211844, 2021). "Activation of the EGFR/AKT signaling pathway correlates to the markedly enhanced migration and invasion of breast cancer cells." (PMID 34294040, 2021). "EGFR signaling was shown to promote migration, invasion, and chemotaxis towards EGF and metastasis in breast cancer cells." (PMID 33670586, 2021). "Epidermal growth factor receptor (EGFR) is a transmembrane protein with cytoplasmic kinase activity and its overexpression has been detected in 30% to 60% of human breast cancer biopsies, being indicative of a poor prognosis." (PMID 34443820, 2021). "We aimed to investigate the role of the EGFR and Src-mediated STAT3 signalling pathway in tamoxifen-resistant breast cancer cells." (PMID 34407787, 2021). "Lapatinib, a dual EGFR/HER2 tyrosine kinase inhibitor, is an effective agent to treat HER2-amplified breast cancer but it failed in gastric cancer (GC) clinical trials." (PMID 34399705, 2021). "In the mixed-breed dog group (n = 18), results showed that EGFR (log FC = 1,8, p = 0.04) and VEGF-B (log FC = 14,7, p = 0.049) genes were upregulated in mammary carcinoma tissue of tumor grade I and III, respectively." (PMID 34679042, 2021). "To verify the potential interplay between FGFR and EGFR, we first validated EGFR_T693 phosphorylation in T47D, BT20, HA‐FGFR2b‐BT549 and a breast cancer organoid grown from a TNBC patient‐derived xenograft (PDX) tumour (Eyre et␣al,2016)." (PMID 34086370, 2021). "Another PTP, known as protein tyrosine phosphatase non-receptor type 12 (PTPN12), is a tyrosine-specific, non-receptor type PTP that exhibits tumor suppressor activity in breast cancer by inhibiting certain RTKs including HER2 and EGFR." (PMID 34884670, 2021). "During breast cancer progression, TGFβ induces single cell migration through a SMAD-mediated pathway involving downstream activation of epidermal growth factor receptor (EGFR), Jun and Rho signaling pathways, and connective tissue growth factor (CTGF)." (PMID 33418880, 2021).